RAB27A (RAB27A, member RAS oncogene family)
Diseases named in the same sentence as RAB27A in open-access papers (continued):
Sharing a sentence is not in itself a finding about the gene and the disease.
breast carcinoma (continued). "Moreover, RAB27A has been reported to promote the invasion and metastasis of breast cancer cells." (PMID 36371494, 2022). "The results show that silencing Rab27a or TRAF3IP2 in the triple negative breast cancer (BC) cell line MDA-MB231 results in the formation of a significantly smaller tumor in a breast xenograft model and significantly extends survival." (PMID 32483202, 2020). "Indeed, the exosomes secreted by breast cancer cells treated with AuNPs functionalized with an anti-RAB27A gene could induce RAB27A gene silencing in bronchial/tracheal epithelial cells." (PMID 28098821, 2017). "Rab27A is a member of the RAS oncogene family that facilitates the growth of mammospheres and has been identified as a mediator of breast cancer stem cells." (PMID 38543182, 2024). "Researchers have discovered that the activation of FAK and JNK regulates RAB27A-mediated exocytosis, facilitating the secretion of the EGFR, which in turn promotes migration and invasion in breast cancer." (PMID 37685910, 2023). "Both Rab27a depletion and an nSMase2 inhibitor (GW4869) significantly inhibit the growth of breast cancer derived from 4T1 cells in mice, which is a drug-resistant model for breast cancer." (PMID 33178688, 2020). "Similar to nSMase2 or Rab27a deletion, ALIX knockdown also leads to a significant decrease in ExoPD-L1 production in breast cancer." (PMID 33178688, 2020). "Here we investigated the roles of Rab27a, a player in exosome release, and TRAF3IP2, an inflammatory mediator, in development and metastasis of breast cancer (BC) in vivo." (PMID 32483202, 2020). "In vitro studies showed that blockade of Rab27a or nSMase2 does not change cell proliferation in prostate cancer, colorectal cancer, or breast cancer, indicating that blockade of exosome biogenesis itself does not cause the suppression of tumor growth." (PMID 33178688, 2020). "The role of Rab27a and TRAF3IP2 in many tumors, including breast cancer, is still unclear." (PMID 32483202, 2020). "Combined Rab27A dependent-release of MMP-9 and exosomes further contributes to the mobilization of a pro-tumoral neutrophil population and supports growth of a mouse mammary tumor and its metastasis in lung." (PMID 23665896, 2013). "Our previous findings indicate that in clinical breast cancer samples, up-regulation of endogenous Rab27B, but not Rab27A, protein correlates with lymph node metastasis and differentiation grade in ER-positive breast tumors." (PMID 21304180, 2010). "First, we performed miRNA sequencing to examine alterations in miRNA profiles in the blood and myocardium of DOX-treated breast cancer-bearing mice intratumorally injected with a lentivirus expressing shRNA targeting Rab27a (ShRab27a) or negative control shRNA (shNC)." (PMID 40360476, 2025). "To explore the effect of breast cancer (BC)-derived sEVs on adipose tissue, we xenografted engineered mouse triple-negative BC (TNBC) cell line 4T1 (4T1/Ctrl) and exosomes secretion impaired 4T1 cells (4T1/Rab27a KO) and those cells were stably expressing a membrane-targeted Lck-GFP." (PMID 37620316, 2023). "Moreover, only Rab27a, not Rab27b, is required for exosome secretion by murine mammary carcinoma cells." (PMID 35053535, 2022). "In addition, prostate and breast cancer cells experiencing a blockade of Rab27a, nSMase2 or PD-L1 failed to grow in WT mice, but grow rapidly in immunodeficient mice." (PMID 33178688, 2020). "The differences in localization and expression of both Rab27 proteins in ER-positive and negative breast cancer cell lines could indicate that Rab27A and Rab27B play different roles depending on the cells’ ER-status." (PMID 21304180, 2010). "Furthermore, the breast cancer cells can induce the expression of Rab27a or TRAF3IP2 in non-malignant breast epithelial 184A1 cells and naïve MSCs via a paracrine mechanism, and demonstrates the impact of breast cancer cells on surrounding non-malignant stroma." (PMID 32483202, 2020).
hepatocellular carcinoma (20 papers, 2015 to 2024). A malignant tumor that arises from hepatocytes. "High tumor expression of Rab27A or Rab27B is associated with poor survival of patients with hepatocellular carcinoma." (PMID 32422889, 2020). "In a study of hepatocellular carcinoma, high tumor expression of either Rab27A or Rab27B was shown to be associated with low patient survival rates, whereas high tumor expression of both Rab27A and Rab27B was associated with poor survival." (PMID 30081925, 2018). "High expression of Rab27A or Rab27B is significantly correlated with advanced TNM classification in hepatocellular carcinoma." (PMID 30081925, 2018). "In the liver, high expression of Rab27a correlates with the development of hepatocellular carcinoma." (PMID 26305877, 2015). "In the liver, high expression of Rab27a correlates with the development of hepatocellular carcinoma, suggesting a high trafficking capacity for exosomes." (PMID 26305877, 2015). "Furthermore, patients with Rab27A (+) or Rab27B (+) exhibit significantly decreased OS compared with those showing Rab27A (−) or Rab27B (−) in hepatocellular carcinoma." (PMID 32432324, 2020). "Moreover, two studies reported the prognostic role of Rab27A that high Rab27A expression indicated poor survival of patients with gliomas and hepatocellular carcinoma (HCC)." (PMID 26070933, 2015). "To determine whether HCV RNA and protein abundances are regulated by exosomal vesicles, we first inhibited exosomal trafficking in human liver carcinoma Huh7 cells by depletion of Rab27a." (PMID 26305877, 2015). "Moreover, the hepatocellular carcinoma patients with high level of Rab27A or Rab27B significantly reduce the overall survival." (PMID 25823663, 2015). "In HLE (hepatoma cell line), the MAPK/ERK-mediated EMT was induced by MHCC97H hepatoma-cell-derived exosomes, and Rab27a knockdown reduced exosome secretion as well as EMT induction." (PMID 32252322, 2020). "The miRNA miR-582-5p is known to suppress the proliferation of a variety of tumors, including hepatocellular carcinoma, colon cancer, and bladder cancer, and this suppression is thought to be related to the target genes CDK1, AKT3, Rab27a, and FOXC1." (PMID 31146370, 2019). "Among those, neutral sphingomyelinase 2 (nSMase2), phosphorylated synaptosome-associated protein 23 (SNAP23) and Ras-related RAB proteins (RAB27A/RAB27B) regulate sEV secretion from different cancer cells like breast cancer, hepatocellular carcinoma (HCC), and colorectal cancer." (PMID 32225076, 2020). "For example, in a hepatocellular carcinoma (HCC) model, CSCs were found to release larger amounts of exosomes, a sub-type of EVs, in comparison with the non-CSC population of the tumor cells, and the secretion was mediated by Rab27a." (PMID 35646668, 2022).
Griscelli syndrome (19 papers, 2007 to 2025). Griscelli syndrome (GS) is characterized by silvery gray sheen of the hair and hypopigmentation of the skin which can be associated to neurological impairment (type 1), immunodeficiency (type 2) or be isolated (type 3). "Similar clinico‐pathological signatures were found in patients with Griscelli syndrome, where biallelic variants in RAB27A are associated with a full syndromic picture and biallelic variants in MYO5A share NDDs and hypopigmentation but not immunodeficiency." (PMID 39420677, 2025). "Autosomal recessive loss-of-function variants in Rab27a cause Griscelli Syndrome, characterized by partial albinism, neurologic deficits, and immunodeficiency secondary to defective lymphocyte granule exocytosis (OMIM#607624)." (PMID 38920696, 2024). "Functional defects in each one of these components are known to cause the hypopigmentation of Griscelli syndrome patients and the diluted coat color of murine models of Griscelli syndrome such as ashen (Rab27A-deficient) mice." (PMID 36126775, 2022). "A mutation of melanosome transport–related genes including Rab27a causes hair graying through the so-called Griscelli syndrome, a rare autosomal recessive disorder." (PMID 36269827, 2022). "Defects in any of these three genes, melanophilin (MLPH), myosin Va (MYO5A), and Rab27a (RAB27A), have been linked with several dilute phenotypes and the autosomal recessive Griscelli syndromes in humans (OMIM #214450, 607624, 609227)." (PMID 32512769, 2020). "Rab27a is the only member of the Rab family whose mutation has been documented to result in a hereditary disease, specifically, Griscelli syndrome." (PMID 24587032, 2014). "Rab27a is the only member of the Rab family whose mutation has been shown to result in a hereditary disease, specifically Griscelli syndrome." (PMID 24587032, 2014). "In support of this region being functionally important, in another Rab associated disease, Griscelli Syndrome, a mutation in the switch 1 region of Rab27A results in a profound phenotype due to failure of the Rab protein to interact with its target melanophilin." (PMID 24516392, 2014). "Genetic alterations of Rab27a cause Griscelli syndrome in humans that manifests as pigmentary dilution of the skin and the hair and variable immunodeficiency due to defects in the transport of melanosomes in melanocytes and lytic granules in cytotoxic T-lymphocytes." (PMID 23029308, 2012). "Mutations in the human RAB27A gene cause Griscelli syndrome." (PMID 17587407, 2007). "Rab GTPases are also implicated in various disorders including RAB7‐related neuropathy, RAB27A‐related Griscelli syndrome, and RAB18‐Warburg micro syndrome." (PMID 39420677, 2025). "In contrast, TLR3 increases melanosome transport to transfer to keratinocytes through Rab27A, the responsible molecule of Griscelli syndrome." (PMID 33371432, 2020). "In human, mutations within any of the genes RAB27A (RAB27A, member RAS oncogene family), MLPH (melanophilin), and MYO5A (myosin VA) encoding for the proteins of the tripartite complex can cause Griscelli syndromes." (PMID 24376820, 2013). "Mutations in genes encoding melanosome transport-related molecules, such as MYO5A, RAB27A and SLAC-2A, have been reported to cause a human pigmentary disease known as Griscelli syndrome, which is associated with diluted skin and hair color." (PMID 22844437, 2012). "Loss of Rab27a prevents secretion from both melanocytes and CTL leading to Griscelli syndrome with albinism and immunodeficiency." (PMID 18266782, 2008). "Mutations within the genes of Rab27a, hMunc13-4, Syntaxin11, and Munc18-2 lead to defective CTL and NK cell function resulting in often lethal immune disorders: Griscelli syndrome (Rab27a) and FHL type-3, -4, and -5 (hMunc13-4, Syntaxin11, and Munc18-2, respectively)." (PMID 24348478, 2013).
Griscelli syndrome (continued). "On the other hand, mutations in the genes encoding MYO5A, RAB27A and MLPH are known to result in one of three subtypes of an autosomal recessive inherited human pigmentary diseases called Griscelli Syndrome (GS), which is mostly characterized as diluted pigmentation in skin and hair." (PMID 22844437, 2012). "The partial redundancy of the Rab27 isoforms was expected given our previous studies on the pathogenesis of Griscelli syndrome where we showed that transgenic heterologous expression of Rab27b in melanocytes could compensate for melanosome clustering and coat color dilution in Rab27a KO (ash) mice." (PMID 17587407, 2007).
Griscelli syndrome type 2 (18 papers, 2012 to 2024). Griscelli syndrome type 2 (GS2) is a rare, inherited condition that affects the skin, hair, and immune system. "Rab27a is implicated in the cause of Griscelli syndrome type 2, a congenital error of immunity that results in partial albinism and hemophagocytic lymphohistiocytosis." (PMID 39679991, 2024). "Rab27a mutation can cause Griscelli syndrome type 2 (GS2), the main symptoms of which are accompanied by immune abnormalities in addition to skin and hair hypopigination." (PMID 39228912, 2024). "Griscelli syndrome type 2 (GS2) is an autosomal recessive immune disorder characterized by biallelic LOF mutations in RAB27A, a gene encoding a small GTPase." (PMID 34868048, 2021). "In line with that, defects of Rab27a cause Griscelli Syndrome type 2 (GS2), an autosomal recessive pigmentation disorder that involves severe immunological defects." (PMID 32570938, 2020). "In fact, mutation in Rab27a is known to be responsible for a PID known as Griscelli syndrome type 2 (GS2), which will be discussed in detail below." (PMID 24478771, 2014). "Griscelli syndrome type 2 is an autosomal recessive human disease caused by mutations in the RAB27A gene that encodes the small GTPase Rab27a." (PMID 24478771, 2014). "Mutations in the RAB27A gene lead to Griscelli syndrome type 2." (PMID 39881889, 2024). "In addition to Griscelli syndrome type 2, mutations in Rab27a are also responsible for serious diseases based on a deficiency in lytic granule exocytosis in T lymphocytes." (PMID 38132356, 2023). "Griscelli syndrome type 2 (GS2) is a pigmentation disorder associated with autosomal recessive mutations in RAB27A." (PMID 35870028, 2022). "Indeed, the Rab27a mutation was the first Rab mutation to be associated with an inherited disease characterized by neurological disorders, a pigmentation defect (partial albinism, silver sheen in the hair) and an immune deficiency, human Griscelli syndrome type 2." (PMID 38132356, 2023). "In 13 out of the 24 (52%) a genetic diagnosis was achieved: PRF1 n = 4 (FHL2), STX11 n = 2 (FHL4), and STXBP2 n = 4 (FHL5), RAB27A n = 2 (Griscelli syndrome type 2), BIRC4 n = 1 (XIAP)." (PMID 30697212, 2018). "Rab27a was the first example of a Rab protein implicated in a human genetic disease: Griscelli syndrome type 2 (GS2), a rare autosomal recessive disorder caused by mutations in the Rab27a gene." (PMID 23164453, 2012). "Further molecular analysis showed that the interaction between Munc13-4 and Rab27a [which is associated with the immune disorder Griscelli syndrome type 2 (GS2)] is crucial for degranulation and cytotoxicity, and that mutations in Munc13-4 abrogate this interaction." (PMID 23346087, 2012). "Since then, the study of familial cases allowed the recognition of genetic alterations directly affecting proteins involved in cytotoxic activity, such as Munc13-4 (FHL-3), Syntaxin 11 (FHL-4), Munc18-2 (FHL-5), RAB27A (Griscelli Syndrome type 2, GS2), LYST (Chediak-Higashi Syndrome, CHS)." (PMID 37426667, 2023). "Defects in RAB27A, LYST, and AP3B1, leading to Griscelli syndrome type 2 (GS2), Chediak-Higashi syndrome (CHS), and Hermansky-Pudlak syndrome type 2 (HPS2), respectively, also cause defective degranulation." (PMID 31396234, 2019).
bladder cancer (17 papers, 2012 to 2024). "MiR-31-5p has been shown to exert tumor suppressive effects in bladder cancer by modulating downstream targets, including RAB27A and KRT6A." (PMID 36199571, 2022). "Circ-BPTF promotes bladder cancer progression and recurrence through miR-21-5p/RAB27A axis, while Circ_0008035 promotes gastric cancer cell proliferation and inhibits apoptosis through miR-599/EIF4A1 axis." (PMID 35444695, 2022). "The cancer-promoting role of Rab27 was confirmed in vitro; knockdown of Rab27A or Rab27B suppressed cell invasion in bladder cancer cells." (PMID 30081925, 2018). "In a study of bladder cancer, knockdown of Rab27A or Rab27B attenuated cell invasion, reduced exosome release, and increased intracellular levels of miR-23b and miR-921." (PMID 30081925, 2018). "In conclusion, the present study demonstrated that Rab27A overexpression facilitates bladder cancer growth, invasion and chemoresistance in bladder cancer, possibly through regulation of NF-κB signaling pathway." (PMID 29088864, 2017). "In conclusion, our study demonstrated that Rab27A is overexpressed in bladder cancer tissues and promotes cancer proliferation, invasion and chemoresistance, possibly through NF-κB signaling pathway." (PMID 29088864, 2017). "Western blot revealed that Rab27A positively regulated the expression of cyclin E, cyclin D1, suggesting Rab27A induces bladder cancer proliferation through cell cycle proteins." (PMID 29088864, 2017). "We checked Rab27A protein in 5 bladder cancer cell lines (5637, RT4, BIU-87, J82 and T24) by western blot and RT-PCR." (PMID 29088864, 2017). "To investigate the role of Rab27A on chemoresistance of bladder cancer cells, we used cisplatin to treat cancer cells and adopted CCK8 viability assay to examine survival rate." (PMID 29088864, 2017). "Western blot analysis showed significant Rab27A overexpression in 7/12 of paired bladder cancer tissues." (PMID 29088864, 2017). "We investigated Rab27A protein in a panel of 87 bladder cancer samples and normal tissues using immunohistochemistry." (PMID 29088864, 2017). "Rab27A protein high expression/overexpression was observed in 39 out of 87 (44.8%) bladder cancer tissues." (PMID 29088864, 2017). "Knockdown of Rab27A suppresses in vitro invasion of bladder cancer cells (T24, FL3)." (PMID 30081925, 2018). "Moreover, Rab27A transfection induces cisplatin resistance in BIU-87 human bladder cancer cells, and Rab27A depletion by siRNA reduces cisplatin resistance in 5637 human bladder cancer cells." (PMID 30081925, 2018). "Here, we checked Rab27A protein in 87 cases of bladder cancer using immunohistochemistry." (PMID 29088864, 2017). "In this study, we demonstrated Rab27A protein was overexpressed in 44.8% bladder cancer samples." (PMID 29088864, 2017). "The rate of Rab27A overexpression was higher in MIBC than that in NMIBC, suggesting Rab27A might contribute to tumor invasion and malignant progression of bladder cancer cells." (PMID 29088864, 2017). "Thus our data identified Rab27A as a positive regulator of mitochondrial function, which confers resistance to mitochondrial apoptosis in bladder cancer cells." (PMID 29088864, 2017). "Thus Rab27A promotes both proliferation and invasion of bladder cancer cells, which correlated well with our immunohistochemical data." (PMID 29088864, 2017). "Rab27a functions as a vesicle docker at the peripheral cytoplasm; a similar pattern of peripheral periostin expression in bladder cancer cells might also suggest a role in EV secretion." (PMID 26981774, 2016). "Knockdown of Rab27A or Rab27B reduces exosome release in T24 and FL3 bladder cancer cells and HeLa cervical cancer cells." (PMID 30081925, 2018). "Besides leukemia, miR-582 has been shown to inhibit the development of solid tumors, including non-small cell lung cancer, bladder cancer, and human colorectal carcinoma, by targeting different gene, such as Hippo-YAP, TTK, and Rab27a." (PMID 35115499, 2022).
bladder cancer (continued). "However, the clinical significance and biological effects of Rab27A in bladder cancer tissues and cell lines have not been investigated." (PMID 29088864, 2017). "The expression rate (63.2%) of Rab27A in muscle invasion bladder cancers (MIBC) was higher than that (34.7%) in non-muscle invasion bladder cancers (NMIBC), suggesting Rab27A is an indicator of muscle invasion bladder cancers." (PMID 29088864, 2017).